CXCR4 (C-X-C motif chemokine receptor 4)
Diseases named in the same sentence as CXCR4 in open-access papers (continued):
Sharing a sentence is not in itself a finding about the gene and the disease.
tumor (continued). "Based on these studies we conclude that there is a complex interaction between CXCR4 expressed on tumor cells with CXCL12 present in the surrounding stroma." (PMID 26161302, 2015). "The interaction between SDF-1 and CXCR4 directs tumor cells to distant organ sites through chemotaxis and homing of metastatic cells." (PMID 25775124, 2015). "In vivo experiments confirmed that downregulation of CXCR4 enhanced cisplatin anticancer activity in tumor-bearing mice, and that this enhanced anticancer activity is attributable to tumor cell apoptosis." (PMID 25544759, 2015). "The CXCL12-induced CXCR4-mediated intracellular signaling enhances tumor growth, cancer cell survival, and metastasis." (PMID 26083776, 2015). "Next, roles of CXCR4-cells-derived exosomes in primary tumor growth and metastatic capacity were examined in two animal models: a tumorogenic/metastatic model using MDA-MB-231 cell line, and a non-tumorogenic model using T47D cell line." (PMID 26528758, 2015). "CXCR4 is a chemokine receptor highly expressed on tumor cells, and activated CXCR4 can directly stimulate cancer cell proliferation." (PMID 26729169, 2015). "Decreased CXCL12 expression further led to dissemination of CXCR4+ tumor cells to distant lymphatic tissues with higher CXCL12 expression." (PMID 25704881, 2015). "Next, we evaluated the expression level of CXCR4 in the metastasized cancer cells in the lung that were more prone to be in the dormant state than the cancer cells in the orthotopic tumor." (PMID 26083776, 2015). "Amine demonstrated that pretreatment of HPV16+ cells with CDV reduces tumor cell metastasis by inhibition of E6 and E7 viral oncogene expression, leading to decreased CXCR4 levels and reduced homing of the cells to the lungs after i.v. injection." (PMID 25609197, 2015). "The underlying mechanism was through down-regulating the expression of CXCR4, a key receptor involved in the cross-talk between tumour cells and its microenvironment, which contributed to its anti-invasive effects." (PMID 25753200, 2015). "The percentage of CD45+/collagen type I+/CXCR4+ cells was significantly increased in the bevacizumab-resistant tumour." (PMID 26635184, 2015). "In particular, CXCR4-mediated interaction that holds cancer (re-)initiating cells within a protective tumor microenvironment (TME) seems to be responsible for resistance to pharmacological treatment, and for relapse, at least in hematopoietic cancers." (PMID 25736399, 2015). "Many studies had demonstrated that CXCR4/CXCL12 axis plays an important role in regulating metastasis of CXCR4 positive tumor cells to the organs expressing CXCL12." (PMID 26526157, 2015). "The tumor and muscle ratio of CXCR4-IR-783 increased from day 1 and peaked at day 3 post injection of CXCR4-IR-783 in mice bearing F5M2 xenograft." (PMID 26472699, 2015). "Recent studies have shown that CXCR4 mutations and WHIM (warts, hypogammaglobulinemia, infections, and myelokathexis syndrome) mutations enhance tumor dissemination and extramedullary involvement within xenograft mouse models of WM." (PMID 26104577, 2015). "Inhibition of the interaction between SDF-1α and CXCR4 by AMD3100 can prevent tumor re-growth, invasion and chemoresistance." (PMID 25843954, 2015). "The HIF-1α/SDF-1/CXCR4 pathway governs the primary and metastatic tumor microenvironments and organ-specific metastases in different malignancies." (PMID 26517240, 2015). "MMPs are downstream targets of CXCR4-mediated signalling, CXCR4 promotes tumour migration and invasion through inducing expression of MMPs via the ERK signaling pathway 8,20,29." (PMID 25753200, 2015). "Metastasis did not require cell-autonomous co-expression of both receptors; instead, the co-implantation of CXCR7- and CXCR4-positive tumor cells was sufficient to promote the metastasis of the latter, and this involved scavenging of extracellular CXCL12." (PMID 25884570, 2015).
tumor (continued). "The paracrine and endocrine effects through CXCL12/CXCR4 are critical for tumor growth, invasion, angiogenesis and metastasis." (PMID 26528758, 2015). "CXCR4 inhibition reduces tumor angiogenesis and in a mouse model, intraperitoneal CXCR4 inhibitors significantly reduced neovascularization in tumors." (PMID 26318034, 2015). "The CXCL12/CXCR4 axis plays a crucial role in tumor development, by many different proposed mechanisms." (PMID 26259237, 2015). "RA-XII at 50 to 100 nM significantly inhibited the CXCR4 expression in the primary culture extracted from 4T1 tumours from 3 mice (p < 0.001)." (PMID 26592552, 2015). "Our results indicate that disruption of CXCR4 signaling by IL-24 results in inhibition of both tumor cell migration and invasion." (PMID 25775124, 2015). "Our data support these findings, since we observed an increase in CXCR4 expression at the protein level from well- to poorly differentiated neoplasms and a significant correlation with tumor grade." (PMID 26259237, 2015). "Activation of the CXCR4/CXCL12 axis can lead to tumor proliferation and can promote neoangiogenesis, cancer cell invasion and metastasis, and EMT." (PMID 26437222, 2015). "In this context, the CXCR4/CXCL12 interaction has been demonstrated to direct CXCR4+ tumor cells to the sites for the development of metastasis." (PMID 26091099, 2015). "Immunohistochemistry (IHC) of tumor xenograft revealed higher CXCR4 expression in F5M2 xenografts than F4 xenografts." (PMID 26472699, 2015). "Results from our sensitivity analysis restrict to studies adjusted for established confounders such as age, gender and tumor stage, suggest that CXCR4 over-expression is probably an independent prognostic biomarker." (PMID 25669980, 2015). "In fact, AMD3100, a specific CXCR4 antagonist, effectively reduced tumour growth and ascites formation in a nude mouse model." (PMID 25765541, 2015). "The expression level of CXCR4 also significantly correlates with tumor size, advanced TNM stage, and shorter overall and disease-free survival." (PMID 25544759, 2015). "Meanwhile, application of this method in in vitro experiments can reduce cell surface expression of CXCR4 and the chemotaxis of tumor cells." (PMID 25866764, 2015). "Elucidation of the function of CXCR4 and its signaling pathway during tumor progression will contribute to an understanding of tumorigenesis and metastasis." (PMID 26318034, 2015). "This has been proposed to contribute to bone turnover as a result of CXCR4-mediated upregulation of IL-6, which is then secreted by the tumor cells to stimulate osteoclastogenesis, thereby enhancing tumor invasion." (PMID 25999952, 2015). "CXCR4 showed cytoplasmic immunoreactivity in 38.2% of tumor samples and 9.1% in normal samples using primary antibodies specific for CXCR4." (PMID 26161302, 2015). "CXCR4 expression at the primary tumor site was correlated only with positivity for lymph node metastasis (P < 0.01)." (PMID 25773070, 2015). "Our observation was consistent with some studies which demonstrated that CXCR4 did express in gene level in vitro or when isolated from the primary tumours in vivo." (PMID 26592552, 2015). "Next we evaluated the expression level of cell surface CXCR4 in the ex vivo cultured cancer cells obtained from the cell line-derived xenograft tumor, and analyzed the percentage of cells that expressed a high level of CXCR4 by flow cytometry." (PMID 26083776, 2015). "In the cell line-derived tumor model, the signal for CXCR4 was much weaker in metastasized cancer cells in the lung than that in the cancer cells of the orthotopic tumors that were strongly stained with the anti-CXCR4 mAb." (PMID 26083776, 2015). "In the pseudo-tumor simulations, we find that individual CXCR4+ cells deplete ligand in their local environment." (PMID 25909600, 2015). "The tumor spheres expressed higher mRNA levels of stemness-related markers such as Oct4, Sox2, Nanog, CXCR4, CD133, Smo, and β-catenin than the parental cells." (PMID 25669973, 2015).
tumor (continued). "Recently, increasing evidence has suggested that alteration of CXCR4 or CXCR7 expression mediated by LPS-TLR4 enhances the invasiveness of tumor cells." (PMID 26288180, 2015). "CXCR4 is expressed in various different tumor types and has been considered the most widely expressed chemokine receptor in most cancers." (PMID 25669980, 2015). "The SDF-1α-CXCR4 interaction promotes tumor progression through the activation of various pathways, including the JAK/STAT, Rho/Rock, PI3K/Akt and MAPK pathways." (PMID 25843954, 2015). "In CLL, low CXCR4 indicates an enrichment of recently divided tumor cells that emigrated from lymphoid tissues." (PMID 25895128, 2015). "The in vivo significance of these findings is documented by the observation that inoculation of CXCR4-cells-derived exosomes in immunocompromised mice enhanced primary tumor growth and metastatic potential." (PMID 26528758, 2015). "Next, to evaluate the role of the CXCL12-CXCR4 signaling in tumor growth, the CXCR4 antagonist AMD3100 was repeatedly administered to the area adjacent to the MDA-MB-231 cell-derived tumors after the xenotransplantation." (PMID 26083776, 2015). "AMD3100 attached to the NPs will also block CXCR4/CXCL12, reducing infiltration of tumor-associated macrophages, enhancing the anti-angiogenic effect." (PMID 27429863, 2015). "The chemokine receptor CXCR4 is widely present in multiple tumors, and a high CXCR4 expression is a predictive marker of tumor metastasis and results in a worse prognosis." (PMID 25846512, 2015). "Analysis of differently expressed genes revealed many dysregulated pathways in the tumour, such as cell cycle, CXCR4 pathway, GPCR-signalling, and neuronal system." (PMID 26998479, 2015). "Our findings also suggest that ANGPTL2 increases bone metastasis by up-regulating CXCR4 in primary tumor cells, thereby enhancing their responsiveness to bone tissue-secreted CXCL12." (PMID 25773070, 2015). "CXCR7 was also shown to potentiate and regulate trans-endothelial migration of circulating CXCR4+CXCR7+-tumor cells, thus leading to enhanced extravasation." (PMID 25955316, 2015). "The data reveals that both CXCL12 expression by fibroblasts and CXCR4 expression on cancer cells, within hypoxic areas of tumors, trigger tumor cell growth, motility and invasiveness." (PMID 25669980, 2015). "Co-activation of both SHH and CXCR4 resulted in higher expression of cyclin D1, while CXCR4 antagonism, resulted in decreased cyclin D1 expression and also blocked maximal MB tumor growth." (PMID 26512695, 2015). "The immunochemical method showed that CXCR4 expression mainly was in cytoplasm or membrane of tumor cells of clear cell RCC (ccRCC)." (PMID 26526157, 2015). "CXCR4, a chemokine receptor involved in tumor cell homing to bone marrow and lymph node was expressed at higher levels in CD5+ compared with CD5− DLBCL (P= .05)." (PMID 25760242, 2015). "More importantly, the observation that CXCR4 expression in ex vivo PDAC samples correlates with patients metastasized disease stage together with current research on experimental tumor models supports the involvement of CXCR4 in the formation of metastasis." (PMID 26091099, 2015). "A role for CXCR4 signaling in HSA metastasis is possible, but the origin of CXCL12 as an autocrine, paracrine or endocrine factor, as well as the role of CXCR4 expressed in inflammatory and stromal cells that form the tumor niche remain to be determined." (PMID 29061949, 2015). "The level of cytoplasmic CXCR4 expression was correlated with tumour progression from TNM stage I to III." (PMID 26404566, 2015). "We studied the expression of CXCR4 by immunostaining tumor xenografts and their parental human CRC and BC cell lines." (PMID 26318034, 2015). "In contrast, other reports showed relatively a high expression level of CXCR4 in the metastatic cancer cells in the tumor models generated by allotransplantation and xenotransplantation of cancer cells in mice." (PMID 26083776, 2015).
tumor (continued). "Functional studies showed IL-24 inhibited tumor cell migration and invasion concomitant with reduction in CXCR4 and its downstream targets (pAKTS473, pmTORS2448, pPRAS40T246 and HIF-1α)." (PMID 25775124, 2015). "As a result of binding to its unique chemokine ligand, CXCL12, CXCR4 is known to activate G protein-mediated signaling cascades, leading to tumor proliferation, survival, angiogenesis, and chemotaxis in multiple cancers." (PMID 25955316, 2015). "Given that the CXCL12/CXCR4 axis is considered to be a critical mediator of cancer–stroma interactions, our study also supports the important contributions of the tumor microenvironment to EGFR cross-talk with other signaling pathways in PDAC." (PMID 25679210, 2015). "The mean expression level in the 468 DLBCLs of the training set was 20% of tumor cells positive for CXCR4 cell surface expression, which was used as the cutoff for CXCR4 overexpression (CXCR4+)." (PMID 25704881, 2015). "CXCR4 overexpression promoted metastatic potential and oestrogen independence tumor growth in vivo, similarly to previous studies performed in MCF7 cells." (PMID 26528758, 2015). "In conclusion, our data indicate that although EGFR expression alone has limited clinical and prognostic significance, EGFR/CXCR4 coexpression identified a subset of PDAC patients with more aggressive tumor characteristics and a significantly worse prognosis." (PMID 25679210, 2015). "CXCR4-neutralization antibody treatment suppressed tumour size, and had extended survival (mean of 54.4 versus 42.1 days, log-rank test P=0.004)." (PMID 26404566, 2015). "Correlating with the tumor cell migration study results, CXCR4, pAKTS473 and pPRAS40T246 protein expression were all reduced in the cells that were treated with AMD3100 alone, IL-24 alone, and AMD3100 plus IL-24 when compared to control cells (P<0.05)." (PMID 25775124, 2015). "The tumor volume and invasion nerve diameter in the sh-CXCR4 group are prominently reduced compared with those in the sh-Control group (P<0.05)." (PMID 25605248, 2015). "Increased expression of CXCR4 induces tumor metastasis through enhanced proliferation of cells by activating molecular pathways and through accelerating vascularization by activating VEGF." (PMID 26318034, 2015). "We also analyzed the expression of CXCR4 (a chemokine receptor), which is critically important for tumor invasion." (PMID 25623281, 2015). "Accordingly, our in vivo experiments in immunocompromised mice inoculated with CXCR4-cell-derived exosomes established that exosomes increased primary tumor growth and metastatic potential." (PMID 26528758, 2015). "Concordantly, multiple studies showed that in different tumor types SDF-1α/CXCR4 interaction resulted in increased metastasis." (PMID 26231656, 2015). "Nonetheless, caution in evaluating the associative results regarding both CXCR4 and CXCL12 expressions in the tumor microenvironment is highly recommended." (PMID 26161302, 2015). "It is widely accepted that the CXCR4/CXCL12 axis underlies the decreased chemosensitivity and disease progression, by directing CXCR4-expressing tumor cells through concentration gradients of CXCL12 to reside in protective niche (such as BM and lymph nodes)." (PMID 25704881, 2015). "The HE staining showed that the sh-CXCR4 mice had significantly decreased sciatic nerve diameters compared with controls, both at the primary tumor site and at 5 mm proximally along the sciatic nerve." (PMID 25605248, 2015). "SDF-1/CXCR4 pathway plays an important role in neoplasia and in metastases formation as CXCR4 is most abundant expressed on cancer cells." (PMID 25866451, 2015). "In conclusion, our results indicate a mutual tropism and paracrine interaction between nerves and cancer cells: peripheral nerve-derived CXCL12 stimulates the proliferation and invasion of CXCR4-positive tumor cells." (PMID 25605248, 2015).
tumor (continued). "These recruited CXCR4+ BMDCs provide favorable environment for the tumor growth by acquiring pro-angiogenic phenotype such as CD45+VEGFR2+ Endothelial Progenitor Cells (EPC), or CD45+Tie2+ myeloid cells." (PMID 26925346, 2014). "In conclusion, these results demonstrate considerable potential of high-affinity CXCR4-blocking agents for OS tumor cell homing suppressive treatment in metastasizing OS complementary to current (neo)-adjuvant chemotherapy." (PMID 24390633, 2014). "Concordant with the transcript expression pattern, 55% (n = 20) tumor showed downregulated expression of CXCR4." (PMID 25114911, 2014). "Blocking of the SDF-1/CXCR4 interaction with AMD3100 inhibits meta-static tumor growth in a mouse hepatic metastasis model of colon cancer." (PMID 24647809, 2014). "The data presented in the study demonstrate that CTCE-9908 is efficacious in preventing spread of tumor cells from primary site by inhibiting invasive and angiogenic functions of CXCL12/CXCR4 axis in primary tumor environment." (PMID 24472670, 2014). "The CXCR4 expression, overall survival, and the clinical characteristics including age, sex, differentiation degree, tumor size, vascular invasion, lymph node metastasis, TNM stage, and T stage were analyzed for 122 IHCC patients." (PMID 25471741, 2014). "The role of the chemokine receptor CXCR4 in the regulation of tumor growth has been recognized as an important issue." (PMID 24728301, 2014). "We have also performed a two-sided Pearson correlation analysis to determine if the relative expression of CXCR4, CXCR7 and CXCL12 in tumours is associated with the relative expression of COUP-TFI." (PMID 24906407, 2014). "These literatures regarding CXCR4 indicate that CXCR4 signaling is not limited to promote tumor progression only; it is also involved in maintaining normal homeostasis of cells/tissue." (PMID 25114911, 2014). "MDSCs are recruited into tumors via the chemokine GPCRs CCR2, CXCR2, or CXCR4 and are believed to promote tumor progression, such as facilitating metastasis in CRC." (PMID 25110692, 2014). "The effect of CXCR4 downregulation on HTB-35 tumor cell proliferation rate was measured by MTS assay." (PMID 24728301, 2014). "High expression of SDF-1 of tumor cells forms a local gradient of the chemokine in the tumor region, recruiting CXCR4-expressing bone marrow-derived progenitor cells to the tumor." (PMID 24877105, 2014). "CXCR4 plays a key role in the metastatic homing of tumor cells to organs expressing a high level of its ligand, SDF-1." (PMID 24618817, 2014). "Our data showed significant downregulated transcription of CXCR4 in 32 out of 63 (51%) primary tumor biopsies (P = 0.007) relative to normal cervical tissues (n = 30)." (PMID 25114911, 2014). "Current evidence indicates that the abnormal expression of chemokines or their receptors, such as CXC chemokine receptor-4 (CXCR4), is positively correlated with the development, progression and metastasis of tumor cells." (PMID 24932293, 2014). "A potential mechanism of CXCR4’s involvement in tumor dissemination and metastasis is through promoting its transendothelial migration at the primary site." (PMID 24475985, 2014). "SDF-1 plays a critical role in the mobilization and recruitment of CXCR4+ BC cells to the neo-angiogenic niches supporting tumor growth and metastasis." (PMID 24674692, 2014). "In studying CXCR4 expression of various tumor cell lines, we have observed that suspension tumor cell lines express high levels of CXCR4 while many solid tumors cell lines express low surface CXCR4 by flow cytometry." (PMID 25514788, 2014). "Experimentally, proof of principle studies demonstrated that inhibition of CXCL12-evoked CXCR4 signaling by respective blocking agents inhibited metastasis in experimental models, achieved by intravenous tumor cell injection." (PMID 24390633, 2014).